INS (insulin)
Diseases named in the same sentence as INS in open-access papers (continued):
Sharing a sentence is not in itself a finding about the gene and the disease.
breast tumor (continued). "In any case, several studies have suggested that although insulin treatment was not involved in breast tumor initiation, it might induce tumor progression by upregulating mitogenic pathways." (PMID 29615978, 2018). "Overall, the data suggests that insulin treatment is not involved in breast tumour initiation, but might induce breast tumour progression by up regulating mitogenic signalling pathways." (PMID 26242987, 2015).
iron deficiency (28 papers, 2011 to 2026). "Conversely, iron deficiency has been associated with insulin sensitivity in rats." (PMID 37299408, 2023). "In young women, correction of iron deficiency anemia decreased insulin levels." (PMID 37299408, 2023).
iron overload (28 papers, 2010 to 2025). "Clinically, insulin secretion in patients with Tangier disease and the ABCA1 mutation is still under investigation." (PMID 30425683, 2018). "Since ABCA1 is expressed in pancreatic β cells, glucose-stimulated insulin secretion might be impaired in Tangier disease patients with ABCA1 mutations." (PMID 31974794, 2020). "In five referred adults with hemochromatosis and iron overload, insulin secretory capacity improved after normalization of iron stores." (PMID 28331855, 2017). "Since pancreatic β-cells express ABCA1, glucose-stimulated insulin secretion may be impaired in Tangier disease patients." (PMID 37233667, 2023). "Iron overload was associated with non-significant increases in serum insulin and HOMA-IR score, and lower HDL cholesterol compared to those with normal or depleted iron stores within the same % BF group." (PMID 34063273, 2021). "However, a case report of four patients with Tangier disease demonstrated that all patients had impaired glucose-stimulated insulin secretion." (PMID 30425683, 2018). "Iron overload, especially in iron-replete women, could intensify the buildup of reactive oxygen species and oxidative damage, ultimately leading to the apoptosis of pancreatic β-cells and a resulting reduction in insulin secretion." (PMID 36432476, 2022). "Specifically, insulin was 39.0 ± 18.8 μIU/ml and 7.7 ± 5.8 μIU/ml and HOMA-IR scores were 10 ± 5 and 2 ± 1, for iron overload cases and controls, respectively." (PMID 24065958, 2013). "The oral glucose tolerance test in patients with Tangier disease indicated a progressive increase in plasma glucose, yet not insulin concentration, suggesting a lower insulinogenic index in patients than in the non-diabetic controls." (PMID 37233667, 2023). "Additionally, total bilirubin, anion gap, insulin, and HOMA-IR were higher in the iron overload group (p = 0.0476, 0.0357, 0.0159, and 0.032, respectively) compared to controls." (PMID 24065958, 2013). "Differences in insulin levels between iron overload cases and controls were observed 2 h post-prandial, but not during the fasting state." (PMID 24065958, 2013). "A clinical report showed that four Japanese patients with Tangier Disease and T2D exhibited lower value of the insulinogenic index insulin compared to non-diabetic TD patients, indicating that cholesterol content and ABCA1 may be critical for insulin secretion." (PMID 34578896, 2021). "We reported that patients with Tangier disease showed the progressively increased plasma glucose concentration after oral glucose tolerance test, indicating a type 2 diabetic pattern; however, plasma insulin concentration did not respond well to glucose increase." (PMID 31974794, 2020).
Myocardial fibrosis (28 papers, 2014 to 2025). "In addition, it is associated with increased insulin resistance, myocardial fibrosis, and left ventricular remodeling because of chronic high blood sugar." (PMID 30261876, 2018). "Activation of this receptor leads to calcium mobilization and PROKR1, a paralog with unusually high sequence similarity to this receptor, has been associated with insulin-mediated Akt signalling and myocardial fibrosis, diastolic dysfunction and impaired capillary formation." (PMID 28270201, 2017). "For instance, excessive lipid accumulation disrupts insulin signaling in cardiomyocytes, leading to cardiac insulin resistance and the activation of profibrotic pathways that promote myocardial fibrosis and exacerbate diastolic dysfunction." (PMID 41158622, 2025). "Pre-treatment with clofibrate decreased cardiac inflammation, reduced myocardial fibrosis and apoptosis, whilst improving insulin sensitivity." (PMID 41007642, 2025). "We therefore sought to evaluate the effect of the DPP-4 inhibitor sitagliptin on myocardial fibrosis, and insulin signaling in chronic myocardial ischemia using a swine model." (PMID 39074126, 2024). "It would be interesting to explore the effect of insulin on the development of myocardial fibrosis using late gadolinium enhancement or extracellular volume derived from cardiac MRI." (PMID 37542280, 2023). "In the context of DCM, weakened insulin signal transduction aggravates abnormal glucose metabolism, culminating in myocardial fibrosis and the progression of diabetic cardiomyopathy." (PMID 38283742, 2023). "We focused specifically on the mechanisms in terms of inflammation, oxidative stress, myocardial fibrosis, mitochondrial function, epicardial lipids, endothelial function, insulin resistance, cardiac hydrogen and sodium exchange, and autophagy." (PMID 37691190, 2023). "In a diabetic rat model, the addition of fluvastatin (with insulin) improved cardiac ACE2 expression and decreased myocardial fibrosis when compared to rats treated with insulin alone." (PMID 36985188, 2023). "The main findings of the present study include the following: a) T2DM was characterized by significant elevation of blood glucose and cardiac enzymes, insulin resistance, disturbed myocardial morphology with myocardial fibrosis and oxidative stress." (PMID 32106580, 2020). "Reduced levels of IGF-1 are associated with higher circulating levels of growth hormone and insulin that promote hypertrophy and myocardial fibrosis." (PMID 32033349, 2020). "It has been well demonstrated that DPP-4 inhibitors reduce fibrosis and modulate insulin signaling in several pathways; however, our study represents the first attempt to study the changes in myocardial fibrosis and insulin signaling with SIT in a swine model of chronic myocardial ischemia." (PMID 39074126, 2024). "Additionally, the overexpression of MG53 specific to cardiomyocytes inhibits insulin signal transduction and exacerbates myocardial fibrosis." (PMID 38283742, 2023). "We speculate that insulin itself could induce cardiomyocyte hypertrophy alongside myocardial fibrosis and collagen accumulation." (PMID 37542280, 2023). "Previously, we suggested that a combination of fluvastatin and insulin may be more effective than insulin-alone treatment in diabetic hearts with regard to reducing myocardial fibrosis and preserving cardiac function and ACE2 expression." (PMID 29682576, 2018). "The myocardial fibrosis changes in the DM + ART (50 mg/kg) group were reduced compared with those in the DM + ART (100 mg/kg) and DM + INS groups." (PMID 33499847, 2021).
uremia (28 papers, 2012 to 2025). A clinical syndrome associated with the retention of renal waste products or uremic toxins in the blood. "Glucose intolerance is another condition associated with uremia, possibly due to decreased insulin secretion." (PMID 32192220, 2020). "Uremia is associated with enhanced susceptibility to ischemia-reperfusion injury and a loss of insulin-mediated cardioprotection." (PMID 24349009, 2013). "Although uremia, glucose and insulin have been found to affect AQP3 gene expression, most studies have been performed in vitro." (PMID 36038817, 2022). "Glycemic control of chronic kidney patients on dialysis presents additional difficulties because both uremia and dialysis can affect insulin secretion and tissue insulin sensitivity." (PMID 34625090, 2021). "An improvement of glucose tolerance and insulin secretion has been described in children with uremia after handling sHPT markers, by phosphate restriction and oral phosphate binders." (PMID 32192220, 2020). "Although insulin binds normally to its receptor in uremia, and receptor density is unchanged, the transfer of insulin resistance by uremic serum suggests a direct contribution of uremic toxins." (PMID 23809614, 2013). "In patients with ESRD, uremia decreases tissue sensitivity to insulin." (PMID 36319967, 2022). "Hepatic clearance of insulin is also decreased in patients with uremia." (PMID 31828166, 2019). "AKTIP was lower in uremia, consistent with the proposals that insulin resistance may promote muscle wasting by inhibition of PI3K/Akt leading to activation of caspase 3 and the ubiquitin-proteasome proteolytic." (PMID 23809614, 2013). "In addition, uremia per se may further substantiate the rate of increased muscle protein breakdown, primarily by worsening the level of insulin resistance." (PMID 24303049, 2013). "There is a prevailing view in the nephrology community that uremia is an insulin-resistant state, so the low IRI in DM patients may indicate poverty of insulin activity." (PMID 30261059, 2018). "In uremia, degradation of insulin in nonrenal tissues such as liver and muscle is impaired and the half-life of insulin is prolonged." (PMID 23431467, 2013). "In addition to insulin, one of the most important regulators of CRF activity is plasma cortisol, therefore impaired cortisol suppression may explain EBD in uremia." (PMID 31191339, 2019).
anorexia nervosa (27 papers, 2012 to 2025). A disorder most often seen in adolescent females characterized by a refusal to maintain a minimally normal body weight, an intense fear of gaining weight, a disturbance in body image, and, in postmenarcheal females, the development of amenorrhea. "In the present study, we have applied this approach to probe the causal effects of glycaemic traits on the risk for psychiatric disorders and observed a significant protective effect of elevated fasting insulin levels on the risk of anorexia nervosa (AN)." (PMID 32920595, 2021). "Using a MR approach which leverages genetic IVs as proxies for three glycaemic traits, we uncovered evidence of a protective effect of elevated fasting insulin on the risk for anorexia nervosa." (PMID 32920595, 2021). "In conclusion, we uncovered evidence of a protective effect of fasting insulin on the risk of anorexia nervosa, with further work now required to further understand the biological mechanisms underpinning this relationship." (PMID 32920595, 2021). "A systematic review highlighted that anorexia nervosa is associated with increased insulin sensitivity whilst bulimia nervosa and binge-eating disorder are associated with decreased insulin sensitivity." (PMID 31546923, 2019). "Anorexia nervosa demonstrates increased insulin sensitivity whilst bulimia nervosa and binge-eating disorders show decreased insulin sensitivity." (PMID 38783222, 2024). "Other non-insulin mechanisms of hepatic GH resistance in anorexia nervosa have also been described, including fibroblast growth factor-21, sirtuin 1, triiodothyronine, leptin and testosterone." (PMID 39665021, 2024). "Patients with anorexia nervosa who have recovered nutritionally have been found to have impaired glucose tolerance and a delayed and lower insulin response than controls." (PMID 33740034, 2021). "A significant protective effect of a natural log transformed pmol/L increase in fasting insulin levels was observed for anorexia nervosa after the application of multiple testing correction (OR = 0.48 [95% CI: 0.33-0.71]—inverse-variance weighted estimate)." (PMID 32920595, 2021). "Fasting insulin in women shows stronger genetic correlations than in men with waist-to-hip ratio and anorexia nervosa." (PMID 33402679, 2021). "Third, insulin sensitivity was similar in lean women and women with anorexia nervosa, which were groups with different fat mass yet similar MetF." (PMID 34926544, 2021). "For example, suggestively stronger inverse genetic correlation between FI and anorexia nervosa in women, compared to men was in line with observed higher insulin sensitivity in individuals with this disease." (PMID 33402679, 2021). "In this regard, it has been reported that patients with anorexia nervosa have lower fasting insulin and glucose levels and increased MCRI; however, these changes were normalized after successful treatment." (PMID 30846785, 2019). "These community-based findings contrast with specialist DM and ED clinics where the young woman with Type 1 DM and anorexia nervosa with overvaluation driving ‘insulin skipping’ is a well recognised presentation." (PMID 31695914, 2019). "Therefore, the authors of this study believe the aberrant interaction between asprosin and insulin is the responsible link for how insulin plays a key role in anorexia nervosa symptoms and behavioral manifestations." (PMID 35462799, 2022). "Finally, compensatory behaviors (insulin reduction/omission and self-induced vomiting), the main symptom of bulimia nervosa and anorexia nervosa subtype binging/purging, was the least frequent symptom in our sample of T1D patients (4.6%)." (PMID 36528643, 2022). "Our analyses showed that anorexia nervosa and education years have a negative genetic correlation with fasting insulin concentrations and insulin resistance, positioning anorexia nervosa as a special case within the psychiatric disorders and potentially differentiating it from OCD." (PMID 31852892, 2019).
anorexia nervosa (continued). "The role of insulin in anorexia nervosa has been described previously." (PMID 31546923, 2019). "Results indicated a positive genetic correlation between genetic variants associated with anorexia nervosa and high-density lipoprotein cholesterol, as well as negative genetic correlations with fasting insulin and fasting glucose." (PMID 31546923, 2019). "Insulin concentrations and HOMA-IR values are very low in anorexia nervosa, which is consistent with literature reports." (PMID 34579156, 2021). "The relationship between fasting insulin and anorexia nervosa was supported by a suite of sensitivity analyses, with no statistical evidence of instrument heterogeneity or horizontal pleiotropy." (PMID 32920595, 2021). "These negative correlations with fasting insulin concentrations mirrored the negative genetic correlations between anorexia nervosa, education years and BF%." (PMID 31852892, 2019).
Cerebral ischemia (27 papers, 2013 to 2025). Restriction of arterial blood supply to the brain associated with insufficient oxygenation to support the metabolic requirements of the tissue. "This study demonstrated for the first time the ability of insulin to decrease the autophagic neuronal death, caused by brain ischemia and reperfusion." (PMID 40699861, 2025). "Our studies demonstrated for the first time the ability of insulin to decrease autophagic neuronal death, caused by brain ischemia and reperfusion." (PMID 39057034, 2024). "It is interesting to note that although insulin causes robust Tyr97 phosphorylation after global brain ischemia, the effect is less (reduced by 39%) compared to insulin treatment alone." (PMID 24223835, 2013). "We speculated that there was relatively little involvement of Fbxo40 in cerebral ischemia-associated hepatic and muscular insulin resistance because IRS1 content remained constant among the groups." (PMID 34943061, 2021). "This work shows that intranasal administration of insulin to rats exposed to cerebral ischemia and reperfusion inhibits AMPK-alpha activity in the hippocampus and frontal cerebral cortex of rats." (PMID 39057034, 2024). "All these data obtained show the ability of insulin to suppress autophagic processes in neurons activated during cerebral ischemia and reperfusion." (PMID 39057034, 2024). "In an adult model of global brain ischemia, single IV bolus of 20 U/kg of insulin resulted in an early increase in pAKT after 30 min and subsequent preservation of CA1 neurons at 14 days of reperfusion." (PMID 38235171, 2024). "In these experiments, the administration of insulin took place before the onset of brain ischemia and daily during reperfusion." (PMID 39057034, 2024). "As far as the antiapoptotic effect of insulin administered to rats with brain ischemia and reperfusion is concerned, it depends first of all on the activation of Akt-kinase." (PMID 39057034, 2024). "Cerebral ischemia exposed rats, compared to control rats, demonstrated higher levels of glucose, hepatic gluconeogenic enzymes, insulin, and insulin resistance index." (PMID 37008060, 2023). "On day one after cerebrovascular ischemia, rats had higher plasma concentrations of fasting blood glucose and insulin." (PMID 37008060, 2023). "Some researchers have observed that rats with middle cerebral artery occlusion show decreased insulin secretory capacity and insulin sensitivity after 1 day of cerebral ischemia, accompanied by elevated fasting glucose and fasting insulin levels." (PMID 36950100, 2023). "Due to the critical role of VRAC channels in cell apoptosis, insulin secretion, anti‐viral immunity, and particularly in cerebral ischemia, there is a pressing need to develop regulators of VRAC channels." (PMID 37278329, 2023). "Several studies have shown that intracerebroventricular injection of insulin after whole brain ischemia upregulates Bcl-2 and Bcl-x protein expression in the hippocampal CA1 region and reduces neuronal apoptosis." (PMID 37256231, 2023). "On the other hand, adiponectin is an antioxidant, anti-inflammatory and insulin-sensitizing adipokine that acts as a protective mediator during cerebral ischemia." (PMID 35624723, 2022). "Cerebral ischemia impaired insulin action, and a reversal effect of AG490 was duplicated in the liver." (PMID 34943061, 2021). "There is reason to believe that intranasally administered insulin can have a neuroprotective effect in the case of cerebral ischemia, but information on this is extremely scarce." (PMID 34769198, 2021). "We used a Jak2 inhibitor, AG490, to explore its effects on inflammation in the cerebral cortical, hepatic, and skeletal muscle tissues, and in the changes of the insulin signaling in a rat model of acute cerebral ischemia." (PMID 34943061, 2021).